HFE (homeostatic iron regulator)
Diseases named in the same sentence as HFE in open-access papers (continued):
Sharing a sentence is not in itself a finding about the gene and the disease.
hereditary hemochromatosis (continued). "Hereditary hemochromatosis (HH), which associates with excessive iron accumulation in body tissues and organs due to the inheritance of one or more mutations in the Human homeostatic iron regulator (HFE) gene, has been shown to lead to OA-like arthropathy." (PMID 35252185, 2022). "Hereditary hemochromatosis is a genetic iron overload disease related to a mutation within the HFE gene that controls the expression of hepcidin, the master regulator of systemic iron metabolism." (PMID 34722560, 2021). "HFE mutations are important gene variations in heredity haemochromatosis and a widespread autosomal recessive disorder correlated with iron excess in Caucasians." (PMID 34582652, 2021). "Increased tissue iron levels are strongly linked to NAFLD in human hereditary hemochromatosis (HH), an autosomal recessive disease in which the body stores too much iron that usually presents with mutations in the HFE gene." (PMID 34441564, 2021). "Hereditary hemochromatosis (HH) is a potentially lethal disease leading to iron accumulation mostly due to mutations in the HFE gene." (PMID 32429125, 2020). "Hereditary hemochromatosis (HH) is caused by mutations in the HFE gene and characterized by systemic iron overload in many tissues, including liver, heart, kidney, brain, and bone." (PMID 33469535, 2020). "Mutations in HFE gene alter iron homeostasis leading to hereditary hemochromatosis and to an increased cancer risk because the accumulation of iron induces oxidative DNA damage and free radical activity." (PMID 32214052, 2020). "Variants in HFE gene are associated with deregulation of iron homeostasis lead to hereditary hemochromatosis and to variably increased risks of cancer." (PMID 32214052, 2020). "For example, mutations in the HFE gene underlying hereditary hemochromatosis (iron overload) have been implicated in several cancers, including breast cancer." (PMID 31170936, 2019). "In one case the presence of homozygosity for the C282Y mutation in the HFE-gene indicates that this patient possibly suffers from hereditary haemochromatosis as well as GD." (PMID 29423829, 2018). "Previously, it was shown that the HFE gene (associated with human hereditary hemochromatosis) has several haplotypes of intronic polymorphisms." (PMID 27317329, 2016). "It was shown that in both iron deficiency and in hereditary hemochromatosis, a disease primarily characterized by elevated iron due to a mutation in the HFE protein, both result in iron deficient crypt cells with elevated levels of DMT-1 mRNA." (PMID 27457588, 2016). "The mutated HFE gene and its protein product are associated with hereditary hemochromatosis (HH), an autosomal-recessive iron overload condition." (PMID 27457588, 2016). "The HFE His63Asp polymorphism (H63D; rs1799945) is located in the hereditary haemochromatosis gene (HFE; standing for High Fe) which is a transmembrane protein with a key role in regulating iron absorption." (PMID 26716680, 2015). "The rs1799945 variant in the HFE (hemochromatosis Fe) gene is the most common genetic factor in hereditary hemochromatosis." (PMID 24825461, 2014). "After identification of the human hemochromatosis protein (HFE) in 1996, it was noted that only a minority of patients were homozygous for the C282Y mutation, indicative of hereditary hemochromatosis." (PMID 25431733, 2014). "Hereditary hemochromatosis is a genetic disorder with mutations in the HFE gene, characterized by iron overload (with a reduced vitamin C stability) and with a predominance of affected men." (PMID 24036531, 2013). "The HFE(C282Y) and HFE(H63D) variants in the iron regulatory HFE gene are the leading cause of adult onset hereditary hemochromatosis (HH), one of the most common genetic diseases in the North American Caucasian population." (PMID 23705020, 2013).
hereditary hemochromatosis (continued). "In CHD patients, the A736V TMPRSS6 polymorphism influenced serum hepcidin levels in individuals positive for mutations in the HFE gene of hereditary hemochromatosis (p < 0.0001)." (PMID 23433094, 2013). "rs1800562, which has been associated erythrocyte traits in multiple studies, corresponds to the amino acid change C282Y in HFE, the most common causal variant of hereditary hemochromatosis (MIM #235200)." (PMID 24058921, 2013). "Hepatic iron overload can be attributed to mutations in the HFE gene, the gene responsible for the iron overload disorder hereditary hemochromatosis, that also cause increases in serum transferrin saturation and ferritin levels." (PMID 21219652, 2011). "HFE is a major histocompatibility complex (MHC) class I-like protein that is mutated in Hereditary Hemochromatosis (HH; OMIM 235200), a common autosomal recessive disorder of iron metabolism." (PMID 21407826, 2011). "Previously, Nef, an HIV-1 accessory protein, was shown to down regulate the expression of HFE protein, a modulator of iron homeostasis that is mutated in the iron-overloading disorder hereditary hemochromatosis." (PMID 21126372, 2010). "In another case, the study of a mutation in the human hemochromatosis protein (HFE), which causes hereditary hemochromatosis, resulted in new insights that are now being used to develop novel diagnostic methods." (PMID 21059217, 2010). "Hereditary Hemochromatosis(HH) is a common genetic disorder of iron overload where the large majority of patients are homozygous for one ancestral mutation in the HFE gene." (PMID 18990219, 2008). "Two common polymorphisms in the HFE gene, the C282Y and the H63D, have been implicated in hereditary hemochromatosis, a disease associated with excess iron absorption." (PMID 17687449, 2007). "Analysis of HFE gene mutations constitutes an important procedure in identifying patients with hereditary hemochromatosis, particularly for patients with iron overload." (PMID 16878186, 2006). "Analysis of HFE gene mutations is an important procedure for identifying patients with hereditary hemochromatosis, particularly in cases of iron overload." (PMID 16878186, 2006). "The value of population screening for HFE C282Y mutations partly depends on the penetrance with respect to the life-threatening manifestations of haemochromatosis." (PMID 15929796, 2005). "The discovery of mutations in the HFE gene that are present in most haemochromatosis patients has provided a useful test in families affected by the disease." (PMID 15929796, 2005). "The high frequency of HFE mutations in the normal population and the availability of a treatment for haemochromatosis led to suggestions that population screening for these mutations would be justified on the basis of both health and cost." (PMID 15929796, 2005). "HFE rs1800562 causing hereditary hemochromatosis presented the highest frequency (7.54%), followed by BTD rs13078881 for biotinidase deficiency (7.08%), FLG rs61816761 for ichthyosis vulgaris and atopic dermatitis (3.38%), and FANCM rs147021911 for Fanconi anemia (3.08%)." (PMID 40763936, 2026). "Hereditary hemochromatosis is a disorder of iron metabolism characterized by increased intestinal iron absorption and progressive parenchymal iron deposition, most commonly associated with homozygous mutations in the HFE gene." (PMID 42037816, 2026). "The HFE C282Y variant, which causes the common type of hereditary hemochromatosis, might be involved in determining the variability of iron overload in patients with thalassemia intermedia." (PMID 39062234, 2024). "HFE gene deficiency leads to hereditary hemochromatosis, a recessive iron storage disorder." (PMID 37435641, 2024). "In addition, the HFE gene is primarily known for its role in hereditary hemochromatosis, a genetic disorder that causes the body to absorb too much iron." (PMID 38956042, 2024).
hereditary hemochromatosis (continued). "Mutations predisposing to hereditary hemochromatosis, particularly the C282Y substitution in the hemochromatosis protein HFE, have been associated with an increased risk of colorectal and breast cancer providing an association between iron and these malignancies." (PMID 37299408, 2023). "The HFE (Homeostatic Fe regulator) gene is commonly mutated in hereditary hemochromatosis." (PMID 36334631, 2022). "HFE itself is involved with iron regulation and has been associated with haemochromatosis." (PMID 34104963, 2021). "Polymorphisms in the HFE gene induces hereditary hemochromatosis and increased iron stores, which could cause iron accumulation in the endocrine pancreas and beta-cell injury." (PMID 33805588, 2021). "Mutations in the HFE gene can lead to hereditary hemochromatosis, an iron overload disorder." (PMID 32564308, 2020). "Notably, the two HFE SNPs included in this study are known to cause forms of haemochromatosis, with rs1800562 (C282Y) causing a particularly serious type, and rs1799945 (H63D) causing a milder form." (PMID 32092884, 2020). "Of note, HLA-H may be mistaken for the HFE gene (associated with haemochromatosis), but, although the HFE protein is similar to the proteins of the MHC class I family, it does not seem to inhibit NK cell activity." (PMID 27701438, 2016). "Furthermore, an influence of genetic factors has been considered, in particular the heterozygosis state of β-thalassemia and mutations in the HFE gene responsible for hereditary hemochromatosis (HH)." (PMID 27077854, 2016). "Interestingly, HFE mutations responsible for hereditary hemochromatosis resulted non significantly associated either to liver siderosis or hyperferritinemia and also liver damage did not result as being influenced by the presence of these mutations." (PMID 27077854, 2016). "Common mutations in the HFE gene, the gene responsible for the iron overload disorder hereditary hemochromatosis, may impact iron status." (PMID 21219652, 2011). "The discovery of the HFE gene in 1996, the high prevalence of C282Y mutations, and the morbidity and mortality associated with untreated hereditary haemochromatosis have presented molecular diagnostics with a potentially attractive test for population screening." (PMID 15929796, 2005). "Furthermore, variants in the HFE gene lead to the accumulation of iron in various organs, sustaining the pathogenesis of hereditary hemochromatosis, coupled to an increased cancer risk due to oxidative damage of DNA and free radical activity, adding these mechanisms to carcinogenesis." (PMID 32214052, 2020). "Hereditary hemochromatosis is the most frequent, identified, genetic disorder in Caucasians affecting about 1 in 1000 people of Northern European ancestry, where the associated genetic defect (homozygosity for the p.Cys282Tyr polymorphism in the HFE gene) has a prevalence of approximately 1:200." (PMID 30514216, 2018). "When mutated, the human HFE gene may be involved in hereditary hemochromatosis, a common autosomal recessive genetic disorder of iron metabolism characterized by excessive intestinal iron absorption that leads to iron deposition in cells and subsequent dysfunction of several organs." (PMID 22530027, 2012). "BRCA1, HFE, and MLH1 are key genes associated with significant health conditions: BRCA1 with breast and ovarian cancers, HFE with hereditary hemochromatosis, and MLH1 with Lynch syndrome, a form of hereditary colorectal cancer." (PMID 38872284, 2024). "Within the cohort, we found that the only EC also was the only patient homozygous for the p.His63Asp (H63D) variant in the homeostatic iron regulator (HFE) gene, one of the main gene involved in human hereditary hemochromatosis (HH)." (PMID 34766580, 2021). "Patients with the common form of hereditary hemochromatosis (HH-1, OMIM 613609) bear in more than 95% of the cases a homozygous mutation in the HFE gene (p.(Cys282Tyr) or C282Y; rs1800562)." (PMID 33457423, 2020).
hereditary hemochromatosis (continued). "Third, it is known that mutations in several genes such as HFE, Hjv, HAMP and FPN result in hereditary hemochromatosis (HH), a disorder that causes excess high iron absorption." (PMID 27099954, 2016). "HFE knockout validation—The simulation of type-1 hereditary haemochromatosis closely matches experimental findings at steady state." (PMID 24244122, 2013). "Human HFE is a MHC class I protein mainly expressed in the liver that, when mutated, can cause hereditary hemochromatosis, a common genetic disorder of iron metabolism." (PMID 22530027, 2012). "The pathophysiology of HFE-derived Hereditary Hemochromatosis and the function of HFE protein in iron homeostasis remain uncertain." (PMID 21407826, 2011). "The human HFE gene (a key component of iron homeostasis in humans) is involved in hereditary hemochromatosis, a common autosomal recessive genetic disorder that is characterized by excessive intestinal iron absorption and progressive iron overload." (PMID 22308152, 2011). "Hereditary hemochromatosis is linked to a higher risk of dementia among male homozygotes who have the p.C282Y mutation in the homeostatic iron regulator (HFE) gene, but not a higher risk of AD specifically, as compared to non-carriers." (PMID 40508094, 2025). "However, homeostatic iron regulator (Hfe), known as a pathogenicity gene of hereditary hemochromatosis with multiple tissues excessive storage of iron, was identified to be slowly downregulated in iWAT during cold exposure based on the RNA-seq data." (PMID 39159807, 2024). "Genetic testing was negative for the C282Y and H63D mutations, resulting in a diagnosis of non-homeostatic iron regulator (non-HFE) related hereditary hemochromatosis." (PMID 39171001, 2024). "In our case, initial genetic testing caused some confusion, as no mutations were detected in the HFE gene, which is responsible for the most common forms of haemochromatosis." (PMID 39687529, 2024). "A liver biopsy showed an almost normal liver specimen with a slight deposition of iron in 2-3% of hepatocytes, and a genetic examination of hereditary hemochromatosis revealed no typical mutations in HFE, TFR2, HJV, HAMP, or SLC40A1." (PMID 36968338, 2023). "Further, our study did not include genetic variation of the HFE gene, which is the main cause of hereditary hemochromatosis." (PMID 36901892, 2023). "The various forms of genetic haemochromatosis are caused by mutations on different iron regulatory genes and are divided into two main groups: HFE-haemochromatosis being caused by mutations on the HFE-gene on chromosome 6 and non-HFE-haemochromatosis." (PMID 33005455, 2020). "Also, we need testing for other HFE gene mutations or other genes involved in hereditary hemochromatosis in the iron-overloaded patients, who were negative for the C282Y, H63D and S65C mutations." (PMID 27335591, 2016). "The homeostatic iron regulator HFE gene, one of the main genes involved in human hereditary hemochromatosis (HH), codes for a major histocompatibility complex (MHC) class I protein, implicated both in iron homeostasis and immunity." (PMID 35353274, 2022).
iron overload (93 papers, 2004 to 2026). "The patient, who carries the HFE H63D mutation, has a predisposition to iron overload, which, combined with the autoimmune condition, pSS, led to the development of PCT." (PMID 40821324, 2025). "Iron overload is either genetic mostly due to hereditary hemochromatosis (HH), caused by mutations in genes implicated in iron sensing and modulation (such as HFE), and β-thalassemia or to acquired conditions such as chronic liver diseases." (PMID 40149659, 2025). "Homozygosity for the H63D variant in the HFE gene, when coinherited with heterozygous β-thalassemia, seems to increase iron overload." (PMID 39062234, 2024). "The C282Y polymorphism of the HFE gene is responsible, alone or in combination with H63D or S65C, for up to 85–90% of hereditary forms of iron overload among northern European populations." (PMID 37686261, 2023). "Variations in the HFE gene have been associated with a reduction in hepcidin release, which can lead to iron overload and the inherited disorder hereditary haemochromatosis (HH)." (PMID 37686261, 2023). "The genotyping of patients with TSAT >40% (iron overload, T = 4) revealed them to be carriers of the SNPs G845A rs 1800562 or C187G rs 1799945 of the HFE gene, which are associated with increased iron storage." (PMID 36555993, 2022). "Mutations in the HFE gene are associated with iron dyshomeostasis and are risk factors for peripheral iron overload." (PMID 34291615, 2021). "It is well established that mutations in the HFE gene are highly prevalent in Caucasian populations and that they are linked to iron overload." (PMID 31658725, 2019). "In this case, we should underscore that the risk of iron overload trebles in carriers of the H63D mutation of the HFE gene (OR: 3.09, p = 0.033)." (PMID 31658725, 2019). "Mutations in the HFE gene are commonly associated with hereditary hemochromatosis in which an iron overload is the consequence of hepcidin deficiency." (PMID 30697143, 2018). "Individuals homozygous for the mutation, which leads to C282Y substitution of tyrosine for cysteine at amino acid 282 in the HFE protein, are at increased risk of iron overload." (PMID 29362711, 2017). "HFE gene mutations appeared to be the main causative agent of inherited iron overload among Caucasians, defined as hereditary hemochromatosis." (PMID 27125837, 2017). "While the direct impact of HFE mutations is evident for iron overload, the direct immunological role of these mutations or of HFE isoforms, such as sHFE, is less clear, particularly in the context of immune defects observed in HH patients." (PMID 28474781, 2017). "In the current study, the relationship between HFE gene p.H63D and p.C282Y mutations and iron deposition occurring during sickle cell anemia progress and their effect on cardiac and liver iron overload have been investigated." (PMID 27095682, 2016). "Allele and genotype frequencies of HFE mutations in patients with iron overload and in the general population from São Miguel Island." (PMID 26501199, 2015). "Association analysis of HFE haplotypes and genotypic profiles with iron overload were also evaluated." (PMID 26501199, 2015). "Approximately 70–76% of patients with iron overload have at least one of the recognized mutations in the HFE gene." (PMID 26197432, 2015). "The frequency of mutations in the HFE gene depends not only on the particular population but also on the criteria adopted for sample selection and the diagnosis of iron overload." (PMID 26197432, 2015). "In order to assess the association of HFE haplotypes (H) and genotypic profiles (GP) with iron overload we calculated relative risk (RR) by comparing the 41 patients against the general population." (PMID 26501199, 2015). "A high risk of developing OA has been observed in iron overload patients, who carry an HFE mutation." (PMID 24825461, 2014). "The H63D polymorphism in the HFE gene is associated with increased iron uptake and ultimately iron overload 42–46." (PMID 23678850, 2014).